EPCAM (epithelial cell adhesion molecule)
Diseases named in the same sentence as EPCAM in open-access papers (continued):
Sharing a sentence is not in itself a finding about the gene and the disease.
ovarian carcinoma (continued). "By contrast, some more recent research demonstrated that IL-8 promoted epithelial to mesenchymal transition (EMT) by increasing the MMP-2, MMP-9 and EpCAM expression, and stimulated the anchorage-independent growth, proliferation, angiogenic potential, adhesion and invasion in ovarian cancer cells." (PMID 35867729, 2022). "Although EPCAM is reported as a membrane protein expressed by any epithelial cell type, its overexpression in carcinomas and in particular by ovarian carcinoma cells is used to distinguish the latter cells from mesothelial and non-epithelial cells in human ascites." (PMID 35055018, 2022). "Ascitic fluid from ovarian cancer patients has previously been reported to contain large amounts of EVs containing EpCAM, and when 12 μl of ascites were tested by flow cytometry, EpCAM was successfully detected in all the ascitic fluid samples with high expression in several of them." (PMID 35135541, 2022). "Given the widespread staining with αSMA MAb but also with EpCAM MAb and their polarized localization in spheroids, we hypothesize that ovarian cancer cells in spheroids undergo the so-called “partial” epithelial-to-mesenchymal plasticity." (PMID 35055018, 2022). "While both individuals with benign and ovarian cancer may have possessed EpCAM-positive EXOs, exosomal microRNA in ovarian cancer patients showed comparable patterns that were substantially different from profiles found in benign disease." (PMID 34639135, 2021). "A more recent study investigating drug-resistant tumor cell phenotypes in the ascitic fluid of epithelial ovarian cancer patients identified that a population of cells that were EpCAM+CD45+ were more resistant compared to EpCAM+ tumor cells and overexpressed ABCA1." (PMID 35582032, 2021). "In a study by the OVCAD Consortium, the authors used a sophisticated approach to detect EpCAM+ ovarian cancer CTCs, which included parallel assessment with qPCR and immunofluorescent staining in blood samples obtained before and after primary treatment (6 months after the adjuvant CT completion)." (PMID 34440558, 2021). "Furthermore, studies show that the mAb catumaxomab killed CD133+/EpCAM+ cancer stem cells by attaching to tumour cells and T cells in cases of advanced ovarian cancer with malignant ascites." (PMID 33920983, 2021). "Specifically, we engineered EpCAM+ OVCAR-5 ovarian carcinoma cells to stably express both mCherry and the ZipGFP-Casp3 apoptotic cell reporter, a GFP variant that only emits fluorescence upon Casp3 cleavage of an inhibitory protease sequence inserted between β1-10 and β11 barrel of protein." (PMID 34415995, 2021). "The primary goal of this study was to test a hypothesis that an internalization of Ec1/EpCAM complex by ovarian cancer cells is slow enough to permit imaging of tumors using [125I]I-PIB-Ec1 a few hours after injection." (PMID 32392820, 2020). "Importantly, we showed that EpCAM-siPKCι aptamer suppressed intraperitoneal tumor development of PRKCI-amplified ovarian cancer cells and prolonged lifespan of tumor-bearing mice." (PMID 32820156, 2020). "With the aid of both in vitro and in vivo experimental models, we showed that an EpCAM aptamer and PKCι siRNA chimera (EpCAM-siPKCι aptamer) not only induced apoptosis in PRKCI-amplified ovarian cancer cells but also suppressed intraperitoneal ovary tumor development." (PMID 32820156, 2020). "Magnetic beads coated with antibodies for the epithelial markers EpCAM, HER2, and MUC1 were applied to enrich CTCs in samples from patients with ovarian cancer, which were followed by multiplex RT-PCR for six genes (EpCAM, HER2, MUC1, WT1, P16, and paired box gene 8)." (PMID 33327605, 2020). "For example, a nanoplasmonic exosome (nPLEX) assay was developed based on transmission surface plasmon resonance (SPR) and arrays of periodic nanoholes functionalized with antibodies to identify exosomal CD24 and EpCAM expression in ascites fluid from ovarian cancer patients." (PMID 32226524, 2020).
ovarian carcinoma (continued). "Furthermore, the EpCAM expressing ovarian cancer stem cells have increased colony and tumour formation capacities and are irresponsive towards doxorubicin and cisplatin treatments." (PMID 32046162, 2020). "The functional consequences and the underlying molecular mechanisms of the complex between EpCAM, claudins and tetraspanins have not yet been explored in the ovarian cancer progression." (PMID 32091301, 2020). "Moreover, it is well recognized that EPCAM positive cells possess tumor-initiating potential, and EPCAM has already been used as a key marker of ovarian cancer stem cells." (PMID 32391123, 2020). "Starting from the hypothesis that the complex between EpCAM, claudins and tetraspanins might influence ovarian cancer progression and chemoresistance, we evaluated whether and which of the molecules associate each other." (PMID 32091301, 2020). "We have previously reported that both paclitaxel and cisplatin, standard chemotherapies used for the treatment of ovarian cancer patients, promotes an increase in the expression of the chemoresistant markers ERCC1 and TUBB3 and the CSC markers CD44, CD133, OCT4A and EpCAM in ovarian cancer cells." (PMID 33023532, 2020). "Using the EpCAM-binding DARPins Ec1 and Ac2, we observed a high activity and specificity in 2D and 3D in vitro ovarian cancer models, a high specificity in patient material and an effective tumor homing in vivo, illustrating the potential of EpCAM-targeted PDT using DARPins." (PMID 32630661, 2020). "Epithelial cell adhesion molecule (EpCAM) is overexpressed in 55%–75% of ovarian carcinomas (OC)." (PMID 32392820, 2020). "A number of DARPin molecules that specifically bind to different tumor-associated antigens, such as human epidermal growth factor receptor 2 (HER2) or the epithelial cell adhesion molecule (EpCAM) overexpressed in breast and ovarian cancer cells, have been developed." (PMID 33081407, 2020). "In contrast, high levels of homogenously distributed EpCAM are detectable on cells of epithelial tumors, and its overexpression represents an independent prognostic marker for reduced survival in patients with breast and ovarian cancer." (PMID 33081407, 2020). "Indeed, third-generation EpCAM-redirected CAR-T cells have been documented to specifically recognize and to kill different EpCAM-positive ovarian cancer cell lines." (PMID 32438548, 2020). "In metastasizing and cisplatin-resistant ovarian cancer cells, claudin-4 or-7/EpCAM/CD82 complex has been detected and the question arose whether the interactions were direct or indirect." (PMID 32091301, 2020). "EpCAM is therefore a suitable target for tPDT of ovarian cancer cells." (PMID 32630661, 2020). "Besides ovarian cancer progression, the complex of EpCAM/claudin-7/CD82 involved in the apoptosis resistance." (PMID 32091301, 2020). "Besides CD83, a large number of the CD83 highly-associated genes (Person correlation >0.5, p < 0.01) within ovarian cancer transcriptome showed higher expression in ovarian cancer cells, especially in the EpCAM+/CD45+ subtypes." (PMID 32823589, 2020). "A previous study revealed that treatment with cisplatin results in the enhanced expression of cancer stem cell markers—including CD44, α2 integrin subunit, CD117, CD133, and EpCAM—and the upregulation of stem cell factors—such as Nanog and Oct4—in residual ovarian cancer cells in in vitro assays." (PMID 31261739, 2019). "EpCAM is a proposed surface marker of ovarian cancer-derived exosomes." (PMID 29499737, 2018). "In addition, EpCAM has been proposed as a marker for ovarian cancer-derived exosomes, but only 1 out of 3 of the ovarian cancer and peritoneal fluid EV samples were positive for EpCAM." (PMID 29499737, 2018). "Although EpCAM-positive exosomes were present in both patients with benign ovarian disease and those harboring ovarian cancer, exosomal miRNA from ovarian cancer patients displayed similar profiles and were considerably distinct from those observed in benign cases." (PMID 28929459, 2018).
ovarian carcinoma (continued). "Notably, this study provided new evidence that siRNA-mediated EpCAM knockdown had an effect on apoptosis by downregulating Bcl-2 expression and upregulating Bax expression in ovarian cancer cells." (PMID 28574829, 2017). "Moreover, interactions between MSC and cancer cells proceed bidirectionally since vice versa, acquisition of some epithelial-like markers including epithelial cell adhesion molecule (EpCAM) can be detected in MSC following coculture with ovarian cancer cells." (PMID 28785589, 2017). "Given that EpCAM-positive CSCs are responsible for tumor resistance to chemotherapy, targeting EpCAM might be a promising approach to effectively eradicate ovarian CSCs as the putative root of ovarian cancer." (PMID 28574829, 2017). "Taken together, these findings led us to hypothesize that EpCAM-positive ovarian cancer cells might play a key role in tumor resistance to chemotherapy as one of the most significant features of CSCs." (PMID 28574829, 2017). "The T cells stably expressing anti-EpCAM CAR displayed a high cell lysis activity towards EpCAM-positive ovarian cancer cells, being able to kill 69.2 ± 8.8% of SKOV3-Luc tumor cells, 68.7 ± 4.8% of CAOV-3 cells, and 91.5 ± 2.6% SW626 cells at an effector to target (E:T) ratio of 40:1." (PMID 28088790, 2017). "In addition, significant differences were observed in progression-free survival between the EpCAM-high and -low groups for patients with stage I–IV ovarian cancer." (PMID 28574829, 2017). "Even though previous studies have focused on the potential association of EpCAM with ovarian cancer survival, there is no unified view on this issue." (PMID 28574829, 2017). "Using an unbiased approach based on principal component analysis of qPCR markers of mesenchymal and epithelial status, we found that CD44v8-10 correlates with epithelial markers such as E-cadherin and EpCAM, while CD44s correlates with mesenchymal markers such as vimentin in ovarian cancer." (PMID 27253518, 2016). "Since EpCAM overexpression was reported to be correlated with epithelial cell proliferation, a technology using microbeads coated with EpCAM antibodies may be used for isolating ovarian cancer exosomes for further analysis." (PMID 25883534, 2015). "Another epithelial marker, EpCAM, was only positive in tumor cells from patient 2, however it is known that primary ovarian cancer cells may lose EpCAM expression in culture." (PMID 26576679, 2015). "Using a highly aggressive and metastatic ovarian cancer cell line (HEY) which sustains high endogenous expression of Oct4A, we show that suppression of Oct4A resulted in the loss of CSC-associated expression of Lin28, Sox-2, EpCAM and CD44." (PMID 26260289, 2015). "In a retrospective study of 500 ovarian cancer patients, EpCAM showed consistently high expression across different tumor stages and subtypes and the protein was over-expressed in cancerous tissues compared with non-cancerous ovarian surface epithelium and inclusion cysts." (PMID 24528603, 2014). "EpCAM antibodies such as MT201 efficiently eliminate cancer cells from ovarian cancer patients." (PMID 24489952, 2014). "Based on both preclinical and clinical outcomes, EpCAM may be served as a possible therapeutic target against epithelial ovarian cancer." (PMID 23902592, 2013). "This has established the need for isolation of specific vesicles populations, To address this, in our initial study, extracellular vesicles of tumor origin were isolated from the blood of women with ovarian cancer using antibodies reactive with epithelial cell adhesion molecule (EpCAM)." (PMID 23908664, 2013). "Interestingly, low to undetectable EpCAM-expressing normal epithelial ovarian cancer cells (HOSE) displayed a variable DNA methylation level of 15±21% (n=10 clones)." (PMID 21694727, 2011).
ovarian carcinoma (continued). "Two hundred and fifty-eight patients affected by EpCAM+ epithelial tumor-related malignant ascites (129 recurrent ovarian cancer) were randomly assigned to receive paracentesis followed by four i.p. infusion of catumaxomab, in a ten-day period, or paracentesis alone." (PMID 22235224, 2011). "Besides its possible prognostic role in ovarian cancer, EpCAM is used as a therapeutic immunotarget for the treatment of malignant ascites." (PMID 21694727, 2011). "Importantly, metastatic and recurrent tumours were found to express significantly higher levels of EpCAM protein when compared with primary ovarian carcinomas." (PMID 21694727, 2011). "Likewise, hMAM and EpCAM gene expression was analyzed in the blood of breast and ovarian cancer patients." (PMID 21129172, 2010). "Although EpCAM is highly overexpressed in breast and ovarian cancers and expressed de novo in certain squamous cell carcinoma relative to their respective normal epithelia, EpCAM expression on colon carcinoma just remains at the high level of normal colonic tissue." (PMID 17211480, 2007). "Preclinical and clinical studies in other epithelial cancers, such as colorectal and ovarian carcinomas, have explored EpCAM-directed approaches, including bispecific T cell engagers (catumaxomab targeting EpCAM x CD3) and chimeric antigen receptor (CAR) T cell therapies." (PMID 40778224, 2025). "The device was used to detect exosome subtypes expressing CD24, EpCAM, and FRalpha proteins in 2 μL plasma samples from 20 ovarian cancer patients and to suggest exosomal FRalpha as a promising biomarker in the early detection and monitoring of ovarian cancer progression." (PMID 38793203, 2024). "However, the application of CellSearch in ovarian cancer may be limited in the setting of low EpCAM expression." (PMID 35545786, 2022). "The shedding of Epithelial cell adhesion molecule positive EVs (EpCAM+ EVs) into the ascites of patients with ovarian carcinoma has been shown previously, as well as the release of tissue-factor-positive EVs (TF+ EVs) from various ovarian carcinoma cell lines, especially those of the serous subtype." (PMID 33466775, 2021). "Once the presence of EpCAM positive CTCs in the blood of patients was confirmed using two methodologies, an expression profile analysis, including a panel of genes related to cell plasticity and ovarian cancer aggressiveness (MUC1, CK19, CXCR4, TIMP1, ALDH1, CD24, CD44, GDF1), was carried out." (PMID 32423054, 2020). "However, not all ovarian carcinomas have sufficiently high EpCAM expression, and there is a risk of overtreatment of patients with tumors expressing low levels of EpCAM." (PMID 32392820, 2020). "Thus, we also asked, whether chemoresistance of human ovarian cancer was so correlated with EpCAM, claudin-4 and −7, and CD82 coexpression/complex formation." (PMID 32091301, 2020). "Hence, expressions of key regulators AKT1, KRAS, EPCAM and CD44 can be correlated to increasing or decreasing the risk of disease progression, so, they can be potential prognostics markers or drug targets in ovarian cancer." (PMID 31752757, 2019). "Besides, ovarian cancer tissue specific protein EpCAM and ApoE were also verified." (PMID 31718609, 2019). "However, even though EPCAM is involved in ovarian cancer regulation, we propose that this EPCAM could be an important gene for possible target gene in ovarian cancer." (PMID 31752757, 2019). "Notably, in ovarian cancer, EpCAM-positive cancer cells were highly present in malignant ascites of recurrent ovarian cancer patients, and the high prevalence of EpCAM-positive cancer cells qualifies this antigen as a prospective target for catumaxomab therapy." (PMID 28574829, 2017).
ovarian carcinoma (continued). "Results from these studies showed very low levels of EpCAM (0.039+0.030 mg/ml) in exosomes of normal individuals and an increase in levels related to stage and severity of ovarian carcinoma, reaching a significantly higher level of 1.42 + 0.228 mg/ml for Stage IV ovarian carcinomas." (PMID 24460816, 2014). "Hence, targeting EpCAM+++ ovarian tumor cells and/or the associated STAT3 pathway in combination with chemotherapy may help achieve durable clinical responses in recurrent ovarian cancer patients." (PMID 23056490, 2012). "In ovarian cancer, the epithelial marker CK7 can be used in combination with other markers (WT1, PAX8, EpCAM) for molecular phenotyping HGSC in tissue biopsies." (PMID 41125825, 2026). "We found that EpCAM and CLDN3 have a pronounced co-expression in various tumor cells, such as OVCAR-3 ovarian cancer cells and NCI-H1781 lung cancer cells." (PMID 40057807, 2025). "It has been demonstrated that in ascites fluid samples of ovarian cancer patients, especially in postchemotherapy samples, the majority of tumor cells are CD45+/EpCAM+ cells derived from the EpCAM+ primary tumor site." (PMID 40525275, 2025). "Preclinical studies consistently show EpCAM CAR-T cells inhibit tumor progression in animal models of colorectal cancer, gastric cancer, prostate cancer and ovarian cancer." (PMID 41417221, 2025). "Preclinically, EpCAM CAR-T cells inhibit growth in colorectal, gastric, prostate and ovarian cancer models." (PMID 41417221, 2025). "Clinical studies have shown that catumaxomab, targeting EpCAM and CD3, effectively controlled malignant ascites in gastric and ovarian cancers." (PMID 40535136, 2025). "An in vitro binding specificity assay was performed using EpCAM-expressing SKOV-3 and OVCAR-3 ovarian cancer cells." (PMID 40445498, 2025). "The combination of anti-EpCAM-moAbs and anti-FRα-moAbs showed a significantly increased positive rate of CTC detection in ovarian cancer patients compared with anti-EpCAM-moAbs alone." (PMID 38275400, 2024). "We analyzed single-cell data from ovarian cancer patients, focusing on cells enriched for the epithelial cancer cell markers CD24+ and EPCAM+." (PMID 39546568, 2024). "Recently, the detection model of CTCs based on the expression of EpCAM, MUC1, and Wilms tumor protein WT1 showed significantly higher specificity than CA125 (92% vs. 82%), especially in early-stage ovarian cancer (74% vs. 58%)." (PMID 38275400, 2024). "The therapeutic potential of FLRT3 blockade to enhance T cell–based immunotherapies in solid tumors was tested in zebrafish xenograft models of ovarian cancer (OVCAR-5) and RD together with EpCAM CAR-T cells or EGFR/CD3 BiTEs, respectively." (PMID 38427724, 2024). "Several bispecific antibodies such as Catumaxomab, MT110 and M701 have been designed to simultaneously bind EPCAM and CD3, to induce a specific T-cell-mediated immune response against ovarian cancer cells." (PMID 40836974, 2024). "We used zebrafish xenograft models of ovarian cancer (OVCAR-5) and rhabdomyosarcoma (RD), together with EpCAM Chimeric Antigen Receptor (CAR-T) cells or epidermal growth factor receptor (EGFR)/CD3 bispecific T cell engagers (BiTEs), respectively." (PMID 38427724, 2024). "In ovarian cancer, an RNA‐based bispecific CD44–EpCAM aptamer was shown to inhibit cell growth and to induce apoptosis by blocking CD44 and EpCAM simultaneously." (PMID 38783892, 2024). "In EpCAM+ ovarian cancer cell line SW626, anti-EpCAM DNA CAR-T cells displayed high lysis activity, being able to kill 91.5% of SW626 cells." (PMID 38612911, 2024). "The relationship between CoCl2 exposure (HIF-1α inducer) and the expression of vimentin, epithelial cell adhesion molecule (EpCAM), and the growth factor receptor (HER2) was examined in ovarian cancer cells." (PMID 36879003, 2023). "This characteristic renders EpCAM a favorable target antigen for the CAR-T therapy of solid tumors, including ovarian cancer." (PMID 38146364, 2023).